TET2 (tet methylcytosine dioxygenase 2)
Diseases named in the same sentence as TET2 in open-access papers (continued):
Sharing a sentence is not in itself a finding about the gene and the disease.
Stroke (continued). "Perhaps a similar mechanism may account for the lower level of inflammation observed at the 14 d post-stroke time point in mice transplanted with Tet2-KO BM cells, although this warrants further investigation." (PMID 39742155, 2024). "However, qRT-PCR revealed that mRNA expression of several key inflammatory markers was lower in the brains at 14 d after stroke of mice that received Tet2-KO BM cells." (PMID 39742155, 2024). "Importantly, measurements of cerebral blood flow during stroke surgeries showed that the extent of ischemia and reperfusion were similar between mice that received WT BM cells and those that received Tet2-KO." (PMID 39742155, 2024). "In addition to evaluating the impact of Tet2-mediated CH on stroke outcome, we also examined the effect of stroke on expansion of Tet2-mutant peripheral blood cells (i.e., reverse causality)." (PMID 39742155, 2024). "It is noteworthy that at 24 h post-stroke we saw no detectable differences in the expression of inflammatory mediators between the two groups, suggesting that Tet2-mediated CH may promote inflammation resolution between the acute and subacute phases of stroke." (PMID 39742155, 2024). "At 24 h post-stroke we found that numbers of neutrophils and macrophages and the levels of these cytokines were similar in mice transplanted with WT and Tet2-KO BM, indicating that the levels of inflammation are initially similar between the two groups acutely after stroke." (PMID 39742155, 2024). "Furthermore, TET2 mutations are highly enriched in patients with ischemic stroke, suggesting a central role of TET2-driven CH in stroke pathogenesis." (PMID 38162500, 2023). "Additionally, TET2 loss‐of‐function mutation was associated with poor functional outcomes at 90 days, independent of age, sex, and initial stroke severity." (PMID 40093911, 2025). "Thus, we tested whether stroke itself could promote expansion of Tet2-mutant leukocytes over the 14 d study period." (PMID 39742155, 2024). "Other studies have identified DNMT3A (30.0%) and TET2 (11.4%) as the most common mutations in individuals with CHIP who experienced a first-ever acute ischemic stroke, and CHIP was specifically associated with recurrent stroke in patients with hyperinflammation." (PMID 38162500, 2023). "Over this relatively short experimental time course, stroke did not promote expansion of Tet2-KO donor cells in any leukocyte subset within the blood." (PMID 39742155, 2024). "As expected, Tet2-KO donor cells expanded in all leukocyte compartments compared to WT cells, however stroke did not accelerate expansion of Tet2 mutant cells in this experimental setting." (PMID 39742155, 2024). "The negligible contribution of the NLRP3 inflammasome to stroke-induced brain injury, may in part, explain why Tet2-mediated CH did not worsen ischemic stroke outcomes in the current study." (PMID 39742155, 2024).
type 2 diabetes (11 papers, 2021 to 2025). "Remarkably, a recent study reported a potential protective association of CHIP with DNMT3A mutation with diabetic polyneuropathy in patients with type 2 diabetes, whereas TET2 mutation showed a positive association." (PMID 36807865, 2023). "TET2 has also been proposed to regulate PPARƴ transcription in adipocytes, which can partly explain the observed Mets and type 2 diabetes association in the present study." (PMID 36009574, 2022). "Mutated TET2 correlated with type 2 diabetes (p < 0.001), the metabolic syndrome (p = 0.002), as well as fasting glucose, HbA1c, and shorter telomeres (p = 0.032, p = 0.003, and p = 0.016, respectively)." (PMID 36009574, 2022). "The TET2 p.Ile1762Val missense mutation rs2454206 correlated with type 2 diabetes and Mets, along with dysregulated glucose metabolism, illustrating epigenetic regulation as a bridge between inherited and environmental causes in the development of disease." (PMID 36009574, 2022). "The investigated TET2 genetic variant (rs2454206), with an amino acid substitution of isoleucine to valine at position 1762, correlated with shorter telomeres and the presence of type 2 diabetes and Mets, and accordingly with fasting glucose and HbA1c levels." (PMID 36009574, 2022). "In our research, although we only used type 1 diabetes mouse model, we believe that the DNP in type 2 diabetes mouse would share the same TET2–TXNIP–NLRP3 axis mechanisms." (PMID 36527131, 2022). "In vascular smooth muscle cell (VSMC) dysfunction mediated by type 2 diabetes conditions, studies have shown that metformin restores TET2 by inhibiting the expression of YTHDC2 and circYTHDC2, thereby preventing the progression of VSMC dysfunction under high glucose conditions." (PMID 38012545, 2023). "For any CHIP, DNMT3A CHIP, TET2 CHIP, and ASXL1 CHIP, the top outcomes reflected CpG sites related to age/aging, alcohol consumption, smoking, and multiple CVD-related traits including body mass index (BMI), type II diabetes, and fasting insulin." (PMID 39070619, 2024).
lupus (10 papers, 2016 to 2025). "TET2, a key regulator of DNA demethylation, has been implicated in immune dysregulation and lupus pathogenesis." (PMID 40386946, 2025). "In Treg cells from patients with lupus, elevated TET2 is involved in the expression of FOXP3, leading to an increased frequency of CD4+FOXP3+T cells in the circulation as well as in renal biopsy specimens." (PMID 40599235, 2025). "IL‐21 can enhance the recruitment of the hydroxymethyltransferase TET2 in the promoter region of BCL6 in lupus patients." (PMID 35343082, 2022). "For instance, high salt diet can trigger enhanced T follicular helper cells (Tfh) in systemic lupus erythematosus (SLE), a T cell compartment implicated in SLE pathogenesis, by inducing DNA methylation per recruitment of the hydroxytransferase Ten-Eleven Translocation 2 (TET2)." (PMID 34512656, 2021). "But at least, our data indicate that lupus patients would be better to reduce salt in-take and the underlying mechanism might provide new therapeutic target for SLE, with interference TET2 and spn to attenuate pathogenic Tfh cells." (PMID 27325182, 2016). "Further, we demonstrated the upregulation of Tet1, Tet2, and Tet3 genes in CD4+ T cells of other two lupus strains, B6/lpr and B6.sle123." (PMID 38153351, 2023). "There was a significantly elevated expression of Dnmt1 and Dnmt3b, as well as Tet1 and Tet2, in CD4+ T cells of three different lupus-prone mouse strains compared to controls." (PMID 38153351, 2023). "In fact, IL‐21 increases the recruitment of TET2 to the BCL6 promoter region in lupus patients, while interferon (IFN)‐α, the signature cytokine for lupus, also increases AIM2 levels, albeit to a lesser degree." (PMID 35538881, 2022). "Our previous studies revealed that TET2 enrichment on the BCL6 promoter was attributed to IL‐21, which potentially explains why lupus T cells have higher BCL6 expression." (PMID 35343082, 2022). "A recent study revealed that TET2 and TET3 are significantly increased in human lupus CD4+ T cells, correlating with increased 5hmc levels at promoter regions and gene activation in human lupus CD4+ T cells." (PMID 34062726, 2021). "Furthermore, Tet2/Tet3 DKO mice tend to develop systemic lupus erythematosus (SLE)-like autoimmunity disease; compared with typical SLE mouse models, Tet2/Tet3 DKO mice seem to have relatively mild disease." (PMID 34222235, 2021).
mastocytosis (10 papers, 2012 to 2026). A clonal myeloproliferative neoplasm characterized by the proliferation and accumulation of neoplastic mast cells in one or multiple organs or organ systems. "Here, we show that expression of the KITD816V allele in mature primary mast cells deficient for TET2 selects for a specific epigenetic signature associated with immune response genes and the pathological inflammation associated with mastocytosis." (PMID 35393954, 2022). "The frequency of TET2 mutation in patients with mastocytosis is 20%–30%; however, < 1% of patients with mastocytosis develop mast cell leukemia." (PMID 35393954, 2022). "We have used a model of somatic mutation of Tet2 for our studies, since in mastocytosis, clonal mutation of TET2 occurs during early hematopoiesis and KITD816V mutation is secondary." (PMID 35393954, 2022). "TET2 loss-of-function mutations also correlate with aggressive forms of mastocytosis, a rare immune disease in humans." (PMID 35393954, 2022). "There are other non-specific oncogenic mutations identified recently in patients with mastocytosis including TET2 (TET oncogene family member 2), a putative tumor suppressor gene and N-RAS." (PMID 28725969, 2018). "In a separate study, prevalence of TET2 mutations in mastocytosis patients was observed in 23% patients out of a total number of 26 (15 ISM, 8 SM-AHNMD, 2 ASM, 1 MCS)." (PMID 26158763, 2015). "Taken together, these studies suggest that cooperation between KIT and TET2 mutations is likely to contribute to the pathogenesis of mastocytosis; the possibility that ASXL1 also plays a role in this process cannot be ruled out." (PMID 26158763, 2015). "The frequency of SRSF2 (23.6%) mutations in patients with mastocytosis appeared to be greater than TET2 mutations, at least in these studies." (PMID 26158763, 2015). "High variance and the rare number of fresh biopsies from patients with mastocytosis, TET2 mutation, and sufficient mast cell burden in the BM biopsies precluded statistical analysis of RNA-Seq on mast cells sorted from mastocytosis patients with KITD816V and TET2 mutation." (PMID 35393954, 2022). "Overall, these clinical findings suggest that the presence of ASXL1 mutations, besides KIT and TET2 may also contribute to the prognosis and survival of mastocytosis patients." (PMID 26158763, 2015). "Furthermore, we show that Tet2 loss-of-function makes KIT D816V-positive mastocytosis amenable to combination therapy with epigenetic modifiers and TKIs." (PMID 24788138, 2014). "TET2 mutations are the most recent genetic lesions described in mastocytosis." (PMID 22905207, 2012). "Clinical and laboratory features of mastocytosis patients stratified according to TET2 mutations." (PMID 22905207, 2012). "In the current article, we provide an overview of epigenetic changes that may occur and be relevant to mastocytosis, including mutations in genes involved in epigenetic processes, such as TET2, DNMT3A and ASXL1, and global and gene-specific methylation patterns in neoplastic cells." (PMID 33803981, 2021). "In TET2-deficient mast cells, chronic activation via the oncogenic KITD816V allele associated with mastocytosis, selects for a specific epigenetic signature characterized by hypermethylated DNA regions (HMR) at immune response genes." (PMID 35393954, 2022). "Both TET2 and KIT mutation are required to provoke a mastocytosis-like disease in mice, although hypermethylated DNA signatures, consistent with TET2 loss of function, have only been described in TET2-deficient mast cells." (PMID 35393954, 2022). "Together, this provides a molecular explanation for the cooperation between TET2 and KITD816V mutations in driving aggressive forms of mastocytosis and adds to a growing body of evidence supporting an immune function for TET2 in differentiated hematopoietic cells." (PMID 35393954, 2022).
mastocytosis (continued). "Taken together, we wondered if TET2 mutation and cooperation with activating KIT mutations in mastocytosis could be an ideal model to further study the importance of TET2 expression for innate immune cell function in differentiated immune cells." (PMID 35393954, 2022). "About TET2, the high percentage of mutations found in aggressive form of human mastocytosis (20.8%) was not confirmed in canine MCT (2.7%)." (PMID 26562302, 2015). "In addition to TET2, ASXL1 appears to also be frequently mutated in patients with mastocytosis (12%-20% cases)." (PMID 26158763, 2015). "In addition to TET2 sequencing, we applied whole genome scanning technologies in our mastocytosis cohort in order to interrogate the genome for the presence of new genetic alterations in this disease." (PMID 22905207, 2012). "In conclusion, TET2, DNMT3A and ASXL1 mutations are also present in mastocytosis and these mutations may affect prognosis, as demonstrated by worse OS in mutated patients." (PMID 22905207, 2012). "The identification of TET2, DNMT3A and ASXL1 mutations in mastocytosis suggest that these defects may alter the epigenetic machinery of the hematopoietic cells in myeloid malignancies, including mastocytosis." (PMID 22905207, 2012). "Moreover, genes whose products influence epigenetic processes including TET2, DNMT3A or ASXL1 may be altered (mutated) in mastocytosis." (PMID 33803981, 2021). "Importantly, we also demonstrate here that the presence of Tet2 mutations alone is not sufficient to initiate mastocytosis, nether in the bone marrow compartment, nor in mature mast cells in the skin." (PMID 24788138, 2014). "The results align with our previous findings, which determined TET2, DNMT3A, SETD2 and BRD4 genes as promising candidates for further analysis, warranting future study in a larger cohort of mastocytosis patients." (PMID 41031827, 2025). "Unlike previous studies that profiled DNA methylation in TET2-deficient mast cells, we show that this signature is profoundly changed upon activation of the KITD816V driver mutation associated with mastocytosis." (PMID 35393954, 2022).
myelofibrosis (10 papers, 2012 to 2023). A partial or complete replacement of the bone marrow stroma by fibrous tissue. "The patient who progressed to myelofibrosis harbored SRSF2, TET2, and MPL mutations at CMML diagnosis and acquired a JAK2 mutation at the time of myelofibrosis transformation." (PMID 36077644, 2022). "Certain mutations in epigenetic regulator genes have been documented in myelofibrosis, including TET2, ASXL1, EZH2, DNMT3A, and IDH1/IDH2 (Singh)." (PMID 31244289, 2019). "Given the important role of GATA transcriptional regulators in myelofibrosis pathogenesis and in Tet2-mutant AML, we performed quantitative PCR for Gata1 and Gata2 in donor-derived MEPs isolated from vehicle- and inhibitor-treated mice." (PMID 29355841, 2018). "TET2 mutations are the most frequently occurring mutations in myelofibrosis not involving the JAK/STAT pathway." (PMID 31244289, 2019). "No primary myelofibrosis patients (n = 6) harboured TET2 mutations." (PMID 23781511, 2013). "Considering the non-driver MPN somatic mutations in the CECs, ASXL1, TET2 and SRSF2 genes were among the most frequently shared mutations and are also known to be the most frequently mutated genes in Myelofibrosis." (PMID 34685741, 2021).
polycythemia vera (10 papers, 2016 to 2022). "In humans, analysis of the TET2 gene in bone marrow cells from 320 patients with myeloid cancers identified TET2 defects in 13 patients with polycythemia vera, all of whom also displayed the JAK2 V617F mutation." (PMID 35456443, 2022). "The aim of our study was to assess the association between the TET2 rs1548483 single nucleotide polymorphism (SNP) and the susceptibility to polycythemia vera (PV), essential thrombocythemia (ET), primary myelofibrosis (PMF) or chronic myeloid leukemia (CML)." (PMID 33271790, 2020). "Polycythemia vera (PV), an MPN characterized by increased red blood cell mass, has been associated with the TET2 gene." (PMID 34660059, 2021). "The TET2 mutant allele T and ASXL1 mutant allele G had the highest frequencies with 0.272 in the PMF and 0.322 in the polycythemia vera (PV) group, respectively." (PMID 28218607, 2017). "When TET2 precedes JAK2, patients are more likely to present with polycythemia vera." (PMID 31784538, 2019).
pulmonary arterial hypertension (10 papers, 2020 to 2025). "Another association with CHIP, and in particular with TET2 mutation, was recently demonstrated for pulmonary arterial hypertension (PAH) within a cohort of 1832 individuals." (PMID 36355225, 2022). "Altogether these findings highlight an association between reduced TET2 and the pathogenesis of pulmonary hypertension in humans and mice." (PMID 35581740, 2022). "In an independent cohort, TET2 expression was decreased in more than 86% of associated pulmonary arterial hypertension (APAH) and idiopathic pulmonary arterial hypertension (IPAH) patients." (PMID 36038916, 2022). "Increased inflammation due to Tet2 loss has recently been associated with pulmonary arterial hypertension in humans as well as in Tet2- deficient mice." (PMID 33520997, 2020). "However, whether it exerts protective or deteriorative effects in various diseases appears entirely distinct, e.g., decreased TET2 expression may exacerbate vasculitis and adverse vascular remodeling of pulmonary arterial hypertension, while elevated TET2 expression causes neuronal damage and loss." (PMID 35235761, 2022). "In those studies, our laboratory found that DNA methylation‐dependent transcription of pulmonary hypertension‐related genes and Tet2 expression is suppressed in the lungs of hypoxic mice." (PMID 35581740, 2022). "Others have found that inherited and acquired TET2 abnormalities occur in only 0.39% of pulmonary arterial hypertension (PAH) cases, but lower expression of TET2 in mononuclear cells was detected, with elevated pro‐inflammatory cytokines, in >86% of inflammation‐associated PAH cases." (PMID 35581740, 2022). "In recent studies, we and others observed that differential DNA methylation and a reduction in TET2 mRNA expression may be key to the pathogenesis of pulmonary hypertension in mice and humans." (PMID 35581740, 2022). "Moreover, we observed that hypoxia‐induced metabolic reprogramming contributes to the reduction in Tet2 expression, and that inhibiting glucose‐6‐phosphate dehydrogenase activity increases pulmonary Tet2 expression in hypoxic mice and reduces pulmonary hypertension." (PMID 35581740, 2022). "The authors identified TET2 mutations and expression in mononuclear cells and showed the complex role, as well as the variety of symptoms, in a cohort study of patients with Pulmonary Arterial Hypertension (PAH) in the absence of mutations in other PAH-related genes." (PMID 33266135, 2020).